LINC02878 (long independently transcribed non-coding RNA 2878)
Synonyms: BREA2
Gene: Long non-coding RNA gene on chromosome 8 (143,696,154 to 143,698,413, forward strand). Ensembl gene ENSG00000181097.
Diseases named in the same sentence as LINC02878 in open-access papers:
LINC02878 is named in the same sentence as 2 diseases in open-access papers, as found by Europe PMC text mining. Sharing a sentence is not in itself a finding about the gene and the disease. The quoted sentences say what the papers report.
tumor (2 papers, 2025). "In vivo, LINC02878 knockdown suppressed subcutaneous tumor growth, reduced lung metastasis, and improved survival in xenograft models." (PMID 41331125, 2025). "This LINC02878/ZNF282/PYCR2 signaling cascade drives proline anabolism, thereby fueling tumor metabolic reprogramming and fostering aggressive malignant progression in CRC." (PMID 41331125, 2025).
LINC02878 also shares sentences with these, for which no sentence is quoted: colorectal cancer (1 paper).